PLN (phospholamban)
Diseases named in the same sentence as PLN in open-access papers (continued):
Sharing a sentence is not in itself a finding about the gene and the disease.
tumor (12 papers, 2017 to 2025). "4T1 cancer cells exhibiting GFP fluorescence (arrows) can be identified in the tumor-associated pLN, confirming the metastatic status." (PMID 35303862, 2022). "On the other hand, I800/I680 image rectified the concentration effect, highlighting the tumor-associated pLN." (PMID 35303862, 2022). "However, signalling pathways like ECM receptor interaction, cell cycle, and TGF‐β signalling showed negative correlations with immune scores, suggesting that their upregulation was linked with an immunosuppressive tumour microenvironment of pLN+ OSCC." (PMID 40038875, 2025). "Univariate analysis indicated that total prostate-specific antigen (tPSA), PI-RADS v2 score, postoperative Gleason grade group (GGG), intraductal carcinoma of the prostate (IDC-P), clinical T2 substaging, and postoperative pathological tumor burden were risk factors for pLN(+) in all patients." (PMID 32923401, 2020). "In summary, our epigenetic analysis not only identifies a significant demethylation of the EGFR promoter in pLN+ OSCC but also highlights the enrichment of pathways critical for tumour progression based on methylated regions." (PMID 40038875, 2025). "Next, we analysed bulk RNA sequencing data derived from 33 tumour samples, including 9 pLN+ and 24 pLN– OSCC." (PMID 40038875, 2025). "AMPK (CAMKK2, CREBs, PPP2R5A/B, PPP2RC/D) and cAMP (BAD, PLN) pathways regulate energy balance and induce autophagy and apoptosis, inhibiting tumour cell growth." (PMID 41007296, 2025). "The differentially expressed genes (DEGs) analysis identified that 7 genes were upregulated and 173 were downregulated in pLN+ tumours compared to pLN– (Log2fold Change > 1; adjusted Wald test p < .05)." (PMID 40038875, 2025). "Increasing evidence has demonstrated that pLN metastasis is a complex process involving tumor immune milieu." (PMID 37254049, 2023). "MMP14 expression in CAFs and the tumour nest at the TSI were significantly associated with pENE + and TME features, such as TB, pLN+, pN2/3, lymphatic invasion (Ly), and perineural invasion (Pn) (p < 0.05)." (PMID 36765296, 2023). "The location of the primary tumor differed significantly between the pLN+ and pLN− groups in the training cohorts (P = 0.008)." (PMID 33680919, 2020). "The tumor-bearing mice have enlarged spleen, mLN and pLN, and B cell expansion in the lung, liver, and kidney, and also significantly shorter lifespan." (PMID 32695674, 2020). "Accordingly, we observed that DTA-1 treatment led to a partial depletion of Tregs in all lymphoid organs including pLN where coincidently it induced a significant increase in the frequency and diversity of tumor-reactive Tregs." (PMID 28638937, 2017). "Predominantly, tumours originated from the upper and lower gingiva (50% both in pLN+ and pLN–)." (PMID 40038875, 2025). "Furthermore, pathways involved in tumour invasiveness and metastasis were also connected and presented in pLN+ OSCC, including clusters named ‘MET promotes cell motility’ and ‘SMAD2/SMAD3:SMAD4 heterotrimer regulates transcription’." (PMID 40038875, 2025). "Thus, NK cells were significantly close to tumor cells with pLN metastasis." (PMID 37254049, 2023). "Our findings suggested that pLN+ OSCC exhibited an active ECM reorganisation, which was conducive to tumour progression and metastasis." (PMID 40038875, 2025). "Furthermore, we performed Gene Set Variation Analysis (GSVA) to estimate the enrichment of gene sets in specific tumours, revealing that the EMT pathway was significantly enriched in the pLN+ sample in contrast to the pLN– sample." (PMID 40038875, 2025).
cancer (9 papers, 2017 to 2025). A tumor composed of atypical neoplastic, often pleomorphic cells that invade other tissues. "The comprehensive exploration revealed the presence of immune‐suppressive signatures, as well as the enrichment of the cell cycle and DNA repair pathway in the pLN+ phenotype, providing critical insights into the mechanisms underlying cancer cell dissemination." (PMID 40038875, 2025). "This suggests that CAFs activate the TGF‐β pathway in cancer cells, facilitating communication and transformation between CAFs and cancer cells, which is exclusive to the pLN+ subtype." (PMID 40038875, 2025). "Our single‐cell and spatial analyses identified that CAFs secrete TGF‐β1/2, enhancing TGF‐βR1/2 expression in cancer cell subclusters in pLN+ OSCC." (PMID 40038875, 2025). "Furthermore, to validate the cellular heterogeneity, we quantified cancer cell proportions in each cluster of pLN+ and pLN– OSCC." (PMID 40038875, 2025). "Given that cancer cell clusters in pLN+ OSCC are ‘TGF‐βI positive’ with enriched EMT functions, we speculate that TGF‐βI is involved in upregulating EMT by inducing the marker genes in these subclusters, such as COL17A1, ITGA6 and CDH13." (PMID 40038875, 2025). "Taken together, our results based on the activation of both upstream genes and downstream receptors may indicate the TGF‐β signalling pathway was indeed activated in cancer cells within the pLN+ group." (PMID 40038875, 2025). "Moreover, both clusters exhibited higher expression levels of TGF‐β receptors TGF‐βR1 and TGF‐βR2, indicating TGF‐β signalling was activated in cancer cells of pLN+ OSCC." (PMID 40038875, 2025). "This could be due to the fact that PLN and DTX pass through the cell membrane via passive diffusion, while FA-PLN are internalized in the cancer cells by the high affinity of targeting ligand (FA) to the FRs in the cancer cells." (PMID 28891336, 2017). "Notably, the ‘Viral Protein Interaction with Cytokine and Cytokine Receptor’ pathway was significantly perturbed in the pLN+ group as compared to the pLN– group, suggesting activation or inhibition of cytokine signalling that possibly affects different aspects of immunity in cancer." (PMID 40038875, 2025). "Therefore, preceding to the snRNAseq findings, we subsequently picked up the top‐50 ranked DEG in each subcluster of cancer cells, and evaluated the signature of CAF and each subcluster in both pLN+ and pLN– samples." (PMID 40038875, 2025). "Finally, four key genes (KLHL30, PLN, LYVE1, and TIMD4) and four clinical factors (Asian, age, grade, and bilirubin) were included in the prognostic model, namely Immunity and Cancer-stem-cell Related Prognosis (ICRP) score." (PMID 32852285, 2020).
infection (5 papers, 2015 to 2021). The state of being infected such as from the introduction of a foreign agent such as serum, vaccine, antigenic substance or organism. "However, infection by AAV6 encoding PLN resulted in a significant decrease of ANF expression down to a level comparable to that of normal iPSC-CMs." (PMID 25923014, 2015). "As expected, infection with ad-dnCAMKII reduced CaMKII-dependent phosphorylation of phospholamban (PLN)." (PMID 33922643, 2021). "Seven days post AAV6 infection, we observed that AAV6-mediated PLN overexpression reduced the frequency of arrythmogenic episodes when compared with non-infected cells." (PMID 25923014, 2015). "These experiments showed that blocking lymphocyte egress did not influence the enhancement of FVC infection seen in the spleen when CD169 was blocked at the pLN." (PMID 30595553, 2019).
cardiovascular diseases (2 papers, 2014 to 2022). "Of the top 50 up-regulated hCM-specific genes we analyzed, 27 of them (54%) showed associations with at least one known cardiovascular diseases and 5 of them (NPPB, TNNT2, NPPA, RYR2, and PLN) were linked to more than 10 different types of cardiovascular diseases." (PMID 24474197, 2014).
metabolic disorders (2 papers, 2016 to 2022). "PPARA, PPARGC1A, and PPARGC1B, which are involved in the fatty acid oxidation of PLN-KO hiPSC-CMs, began to decline at day 30, while genes involved in glucose utilization, such as GNPNAT1, PGM3, and GFPT1, were upregulated, indicating that energy metabolism disorders began to occur." (PMID 35334215, 2022).
bacterial infection (1 paper, 2008). "Of these, only 3 genes (CA3, KRT17 and PLN) have been annotated, and none of these previously have been shown to be involved in the response to bacterial infection." (PMID 18811943, 2008).
myopathy (1 paper, 2017). A disease of the muscle in which the muscle fibers do not function properly. "Our findings showing that PLN overexpression causes myopathy and muscle atrophy whereas SLN upregulation counters it, adds to the notion that PLN and SLN may not be functionally redundant." (PMID 28278204, 2017).
PLN also shares sentences with these, for which no sentence is quoted: cardiac arrhythmias (5 papers); right ventricular cardiomyopathies (4); Danon disease (3); Left ventricular dilatation (3); familial atrial fibrillation (2); genetic disease (2); hyperlipidemia (2); idiopathic dilated cardiomyopathy (2); myocardial ischemia (2); myocarditis (2); takotsubo syndrome (2); Ventricular hypertrophy (2); amyloidosis (1); Barth syndrome (1); Brugada syndrome (1); cardiac amyloidosis (1); cardiac sarcoidosis (1); Cardio-cutaneous syndromes (1); cardiofaciocutaneous syndrome (1); catecholaminergic polymorphic ventricular tachycardia (1); coronary artery diseases (1); death (1); diabetic cardiomyopathy (1); energy metabolism disorders (1); epilepsy (1); familial thoracic aortic aneurysms and dissections (1); glycogen storage diseases (1); Heart (1); hypertrichotic osteochondrodysplasia (1); ischemic cardiomyopathy (1).
A further 15 diseases each share a sentence with PLN in 1 paper.